EGFR (epidermal growth factor receptor)
Diseases named in the same sentence as EGFR in open-access papers (continued):
Sharing a sentence is not in itself a finding about the gene and the disease.
non-small cell lung carcinoma (continued). "The epidermal growth factor receptor (EGFR) inhibitors such as erlotinib and gefitinib are widely used for treatment of non-small cell lung cancer (NSCLC), but they have shown limited efficacy in an unselected population of patients." (PMID 30679620, 2019). "Collectively, osimertinib would be a more competitive first-line treatment for advanced non-small cell lung cancer patients beyond the first-generation EGFR-TKIs and further OS data of FLAURA study was pending to decipher the order issue." (PMID 31023335, 2019). "High levels of EGFR are observed in various cancers, including non-small cell lung cancer, colorectal cancer, pancreatic cancer, esophagogastric cancer, and GC." (PMID 30530570, 2019). "E-cadherin has repeatedly been shown to be both a marker and driver of EGFR sensitivity in non-small cell lung cancer." (PMID 30921351, 2019). "For instance, it has been shown that non-small cell lung carcinoma patients display an initial efficient response to EGFR tyrosine kinase inhibitor; however, this therapeutic approach rapidly fails following sustained drug administration." (PMID 31075989, 2019). "DUXAP9 has also been found to promote non-small-cell lung cancer progression by directly binding with Cbl-b and thus augmenting EGFR signaling." (PMID 31409759, 2019). "For example, a member of the ERBB family ERBB2, also known as HER2, is amplified in about 30% of all breast cancers and overexpression of EGFR (epidermal growth factor receptor) is found in more than 50% of non-small cell lung cancer." (PMID 31333463, 2019). "Identification of activated epidermal growth factor receptor (EGFR) mutations and application of EGFR-tyrosine kinase inhibitors (EGFR-TKIs) have greatly changed the therapeutic strategies of non-small-cell lung cancer (NSCLC)." (PMID 30823937, 2019). "E-cadherin has previously been identified as a potential biomarker for treatment response to EGFR inhibition in non-small cell lung cancer." (PMID 30800218, 2019). "In non-small cell lung cancers, the signaling from EGFR to the phosphorylation of Akt and ERK was correlated with the sensitivity of gefitinib." (PMID 31514441, 2019). "Resistance to EGFR tyrosine kinase inhibitor (TKI) in non-small cell lung cancer (NSCLC) has been attributed to MET amplification." (PMID 31480591, 2019). "The EGFR signaling pathway can also regulate PD-L1 expression through the IL-6/JAK/STAT3 pathway in non-small cell lung cancer (NSCLC) cells." (PMID 31480382, 2019). "Regarding the literature, the modulation of MHC I receptors by anti-EGFR TKIs is supported by other data on non-small-cell lung cancer cells." (PMID 31546690, 2019). "Precision medicine has revolutionized the treatment of patients in EGFR driven non-small cell lung cancer (NSCLC)." (PMID 31857889, 2019). "In some types of cancers (e.g., non-small cell lung cancer, or colorectal cancer), treatment with anti-EGFR therapy has resulted in the intratumoral clonal selection of therapy-resistant cells." (PMID 31544832, 2019). "Targeted therapy with tyrosine kinase inhibitors (TKIs) against the human epidermal growth factor receptor (EGFR) is currently the most common form of personalised treatment for non-small-cell lung carcinoma (NSCLC)." (PMID 30953094, 2019). "Histologic transformation of EGFR mutant non-small cell lung cancer to small cell lung cancer is an important mechanism of resistance to EGFR tyrosine kinase inhibitors that occurs in approximately 3–10% of EGFR mutant non-small cell lung cancers." (PMID 31816897, 2019). "Pathologically, the aberrant expression of EGFR was found in more than half of non-small-cell lung cancer (NSCLC) patients 28 and mutations in the kinase domain of the EGFR gene are detected in approximately 40% of East Asian lung adenocarcinoma patients." (PMID 31588184, 2019).
non-small cell lung carcinoma (continued). "For the EGFR, gefitinib halts cell growth at concentrations of approximately 40 to 60 nM in non-small cell lung cancer and epidermoid carcinoma cells, among others." (PMID 30921351, 2019). "Prognosis is informed by patient age, Karnofksy performance status, extent of disease, and in recent years, molecular marker status, such as HER2/neu in breast cancer and EGFR in non-small cell lung cancer." (PMID 31508362, 2019). "The drug gefitinib, a specific inhibitor of EGFR tyrosine kinase, has been shown to suppress the activation of EGFR signaling for survival and cell proliferation in non-small cell lung cancer cell lines." (PMID 35582586, 2019). "As promising results were obtained in preclinical analyses with antisense oligonucleotides for the treatment of non-small-cell lung carcinoma and prostate cancer, possibility to silence EGFR and EGFRvIII gained more attention." (PMID 32089685, 2019). "For example, a phase 1 clinical trial that targomiRs, minicells loaded with miR-16-based mimic miRNA and targeted to EGFR, is being evaluated in patients with malignant pleural mesothelioma and non-small cell lung cancer." (PMID 31709180, 2019). "Using per-cancer and pan-cancer settings, the model predicted both known, including EGFR inhibitors in non-small cell lung cancer and tamoxifen in ER+ breast cancer, and novel drug targets, such as vinorelbine for TTN-mutated tumors." (PMID 30704458, 2019). "Osimertinib is a mutant-selective EGFR inhibitor that is effective against non-small cell lung cancer (NSCLC) in patients with the EGFR-T790M mutation, who are resistant to EGFR-tyrosine kinase inhibitors (EGFR-TKIs)." (PMID 30875919, 2019). "Approximately 10–20% of patients with non-small-cell lung carcinoma (NSCLC) in Western countries and 40–50% in East Asia have tumors harboring somatic activating mutations in EGFR." (PMID 30609749, 2019). "This phenomenon has been observed in more than one-third of patients with non-small cell lung cancer treated with EGFR tyrosine kinase inhibitors and can be often misinterpreted as progression on conventional imaging response criteria." (PMID 31781977, 2019). "Mutations in the EGFR also confer drug resistance in non-small cell lung cancer (NSCLC) and other tumor types, e.g., the T790M mutation, alternative pathways activation, loss of function of the EGFR-mediated apoptosis pathway." (PMID 31164821, 2019). "Acquired resistance to epidermal growth factor receptor-tyrosine kinase inhibitors (EGFR-TKIs) has been a major obstacle in the treatment of non-small cell lung cancer (NSCLC) patients." (PMID 31043587, 2019). "In another mathematical model, the authors sought to reconcile the development of resistance to epidermal growth factor receptor inhibitor in non-small cell lung cancer (NSCLC) with the changes in the TME." (PMID 31075118, 2019). "Epidermal growth factor receptor (EGFR) tyrosine kinase inhibitors (TKIs) are being wildly used as target therapy in non-small-cell lung cancer (NSCLC)." (PMID 31196210, 2019). "Epidermal growth factor receptor (EGFR) tyrosine kinase inhibitor (EGFR-TKI) is used for non-small cell lung cancer, and one of the major adverse effects in EGFR-TKI is diarrhea." (PMID 31427707, 2019). "The possibility that RET fusions drive resistance to EGFR inhibition is corroborated by recent studies showing that RET fusions confer resistance to osimertinib in non-small cell lung cancer patients." (PMID 31653970, 2019). "In a landmark study, MET amplification was discovered as a resistance mechanism in a gefitinib-adapted subline of the EGFR exon 19 mutant non-small cell lung cancer cell line HCC827." (PMID 35582596, 2019). "Overexpression of epidermal growth factor receptor (EGFR) has been established as a valid therapeutic target of non-small cell lung cancer (NSCLC)." (PMID 31651282, 2019).
non-small cell lung carcinoma (continued). "Few previous studies of patients with non-small cell lung cancer (NSCLC) and leptomeningeal metastases have used liquid biopsy of cerebrospinal fluid (CSF) to identify epidermal growth factor receptor (EGFR) mutations and guide therapy." (PMID 31396478, 2019). "uPAR promotes the resistance to tamoxifen in breast cancer by activated ERK1/2 activity, and confers the resistance to gefitinib in non-small-cell lung cancer through activated EGFR/pAKT/survivin signal pathway." (PMID 30873379, 2019). "Still, the interest in the structure/function relationships of EGFR remains unabated because of the crucial role played by oncogenic EGFR mutants in driving non-small cell lung cancer (NSCLC)." (PMID 30959819, 2019). "In our previous study, we showed the reversal of glycolytic phenotype in EGFR-driven non-small cell lung cancer cells and xenografts in response to EGFR inhibitors." (PMID 31252559, 2019). "The U.S. FDA has approved Giotrif for the management of locally advanced or metastatic patients with non-small cell lung cancer with the following characteristics: EGFR del19 or L858R." (PMID 31671561, 2019). "Epidermal growth factor receptor (EGFR) tyrosine kinase inhibitors, such as erlotinib, are considered effective therapies for EGFR mutation positive non-small cell lung cancers." (PMID 31799190, 2019). "A good efficacy of nimotuzumab on non-small cell lung cancer (NSCLC) indicated that intermediate affinity for EGFR showed a low toxicity profile and allowed its use on long-term chronic treatment." (PMID 30733972, 2019). "EGFR-tyrosine kinase inhibitors (EGFR-TKIs) have achieved remarkable outcomes in the treatment of patients with EGFR-mutant non-small-cell lung cancer, but acquired resistance is still the main factor restricting their long-term use." (PMID 31832192, 2019). "Previous studies in patients with non-small cell lung cancer have shown that proteins commonly used to screen tumor biomarkers can be used as exosome biomarkers of non-small cell lung cancer, such as EGFR, CD151, CD171, tetraspanin 8, and NY-ESO-1." (PMID 30733650, 2019). "Therapies targeting EGFR using TKIs and antibodies directed against EGFR-ligand binding site have provided remarkable responses in human non-small cell lung cancer and metastatic colorectal cancer, respectively." (PMID 31139331, 2019). "In non-small-cell lung cancer (NSCLC) patients, the frequency of EGFR-TK domain mutations was found to be higher among Asian patients versus patients of other ethnicities (30% versus 8%, p < 0.001)." (PMID 30790152, 2019). "Tyrosine kinase inhibition has proved to be a promising strategy to support cancer therapy against non-small cell lung carcinoma (EGFR inhibitors) and leukemic malignancies (CML: ABL inhibitors; AML: FLT3 inhibitors; ALL: ABL inhibitors)." (PMID 31614680, 2019). "Previously, we reported that nicotine reduces erlotinib sensitivity in a xenograft model of PC9, an epidermal growth factor receptor-tyrosine kinase inhibitor (EGFR-TKI)-sensitive non-small-cell lung cancer cell line." (PMID 30818860, 2019). "Recently, enhanced STAT3 activation was found in an EGFR-driven, patient-derived xenograft model of non-small cell lung cancer, contributing to acquired EGFR resistance." (PMID 31422383, 2019). "One clinical trial of EGFR-specific CAR-T regarding non-small cell lung cancer (NCT01869166) had reported its preliminary results." (PMID 31023335, 2019). "Several lines of evidence suggest that epidermal growth factor receptor (EGFR) is an attractive target for non-small cell lung cancer (NSCLC) therapy." (PMID 31052435, 2019). "EGFR overexpression and EGFR-mediated signaling-pathway dysregulation have been observed in tumors from patients with several cancers, especially non-small cell lung cancer." (PMID 31137590, 2019).
non-small cell lung carcinoma (continued). "Epidermal growth factor receptor (EGFR) is the key molecular target for non-small cell lung cancer (NSCLC) due to its major contribution to complex signaling cascades modulating the survival of cancer cells." (PMID 30925736, 2019). "Phenotypic changes include the enrichment of tumor-initiating cells, the histological transformation from EGFR-mutant non-small cell lung cancer to small cell lung cancer, and epithelial–mesenchymal transition resulting in therapeutic tolerance/resistance." (PMID 31816897, 2019). "Pneumonitis is the leading cause of death associated with the use of epidermal growth factor receptor (EGFR) tyrosine kinase inhibitors (EGFR-TKIs) against non-small cell lung cancer (NSCLC)." (PMID 31426531, 2019). "It has been demonstrated that the kinase activity of AXL is required for erlotinib resistance in EGFR-mutant non-small cell lung cancer (NSCLC) models." (PMID 31694201, 2019). "The development of epidermal growth factor receptor-tyrosine kinase inhibitors (EGFR-TKIs) has dramatically improved the prognosis of patients with EGFR-mutant non-small-cell lung cancer (NSCLC)." (PMID 31892337, 2019). "Our aim was to explore potential strategy to overcome the epidermal growth factor receptor (EGFR) inhibitors resistance in non-small cell lung cancer (NSCLC)." (PMID 31316001, 2019). "Osimertinib is an oral epithelial growth factor receptor tyrosine kinase inhibitor (EGFR-TKI) used primarily in the treatment of metastatic non-small cell lung cancer." (PMID 31467750, 2019). "Here, we explored the therapeutic effects of co-inhibition of PI3K and mTOR in non-small-cell lung cancer (NSCLC) cells with different EGFR status." (PMID 31262325, 2019). "The beneficial impact of EGFR TKIs has been mainly investigated by the combination of erlotinib and gefitinib with radiotherapy or chemoradiotherapy in non-small cell lung cancer (NSCLC) as well as HNSCC." (PMID 30621219, 2019). "First-generation epidermal growth factor receptor (EGFR) targeted kinase inhibitors (TKIs) are still used in selected non-small cell lung cancer (NSCLC) patients despite the resistance." (PMID 30842489, 2019). "A recent report found that EGFR-tyrosine kinase inhibitor (erlotinib) resistant non-small cell lung cancer (NSCLC) has increased EHMT2 expression." (PMID 31775874, 2019). "Liquid biopsy has emerged as an alternative source of nucleic acids for the management of Epidermal Growth Factor Receptor (EGFR)-mutant non-Small Cell Lung Cancer (NSCLC)." (PMID 31416192, 2019). "Epidermal growth factor receptor (EGFR) inhibitors have been successfully used as co-drugs to improve the prognosis of non-small cell lung cancer (NSCLC) expressing EGFRs." (PMID 30695050, 2019). "Recently, completed phase II trials have evaluated linsitinib combination therapies with paclitaxel in patients with recurrent ovarian cancer and with erlotinib in metastatic EGFR-mutant non-small-cell lung cancer (NSCLC) patients." (PMID 31467485, 2019). "In non-small-cell lung cancer, high expression of EGFR correlates with poor survival and anti-EGFR agents have greatly improved the progression-free survival over standard chemotherapy." (PMID 31886203, 2019). "EGFR inhibitors are used in the treatment of selected cancer patients; especially those with non-small cell lung cancer." (PMID 30626422, 2019). "In the present study, we studied the association between DepOR and progression-free survival (PFS) in patients with advanced non-small cell lung cancer (NSCLC) treated with epidermal growth factor receptor tyrosine kinase inhibitor (EGFR-TKI)." (PMID 31602263, 2019). "The epidermal growth factor receptor (EGFR) pathway is a well-studied oncogenic pathway in human non-small cell lung cancer (NSCLC)." (PMID 31387256, 2019). "Up to 22% of patients with non-small cell lung cancer (NSCLC) who progress on first-line EGFR-TKIs have MET amplification or other MET-based mechanisms of resistance." (PMID 31613934, 2019).
non-small cell lung carcinoma (continued). "Here, we report the detection of EGFR L792 mutations, a non-covalent mechanism of osimertinib resistance, using Guardant360 cfDNA testing in a patient with metastatic EGFR-mutant non-small cell lung cancer (NSCLC) whose disease progressed on osimertinib." (PMID 31632838, 2019). "Tyrosine kinase inhibitors for epidermal growth factor receptor (EGFR TKIs) greatly improved clinical outcomes of patients with non-small cell lung cancer (NSCLC)." (PMID 31637005, 2019). "Clinical trials have shown that inhibition of EGFR by TKIs such as gefitinib or antibodies such as cetuximab have proven effective in human non-small cell lung cancer and metastatic colorectal cancer, respectively." (PMID 31139331, 2019). "The introduction of EGFR-TKIs in clinical practice changed the strategy for the treatment of non-small cell lung cancer (NSCLC)." (PMID 30153300, 2018). "In a study, Rizzo and colleagues investigated the association between conventional CT features and EGFR, ALK, KRAS mutations in non-small cell lung cancer." (PMID 30547844, 2018). "Epidermal growth factor receptor-tyrosine-kinase inhibitors (EGFR-TKIs) have been used to treat non-small cell lung cancers." (PMID 30619741, 2018). "The EGFR is commonly overexpressed in non-small cell lung cancer (in 89% squamous cell carcinoma; 41% adenocarcinomas), and therefore, it is considered a potential target for cancer therapy." (PMID 30127783, 2018). "For example, there were only two responders and 5 patients with stable disease (SD) out of 11 in a phase I study of epidermal growth factor receptor (EGFR)-directed CAR-T cells for relapsed/refractory EGFR+ non-small cell lung cancer patients." (PMID 29364163, 2018). "Despite rapid advances in high-throughput screening technologies, only a handful of predictive biomarkers are routinely tested in TB to guide treatment decisions (e.g., EGFR in non-small cell lung cancer or KRAS in colorectal cancer)." (PMID 29544535, 2018). "As a first specific example, we focused on gefitinib, an epidermal growth factor receptor (EGFR) tyrosine kinase inhibitor approved for treatment of patients with non-small-cell lung cancer." (PMID 29276046, 2018). "Through the result of KEGG pathway enrichment showed that two pathways (hsa05223: Non-small cell lung cancer and hsa01521: EGFR tyrosine kinase inhibitor resistance) were directly associated with EGFR-TKI resistance." (PMID 30400936, 2018). "Epidermal growth factor receptor (EGFR)-tyrosine kinase inhibitor (TKI) is the standard of care for patients with EGFR-mutant advanced/metastatic non-small cell lung cancer (NSCLC)." (PMID 30410675, 2018). "Sixty Han Chinese advanced non-small cell lung cancer patients received erlotinib monotherapy and, for each participant, 76 candidate genes (related to EGFR signaling, drug metabolism and drug transport pathways) were sequenced and analyzed." (PMID 29695969, 2018). "Epidermal growth factor receptor (EGFR) mutations and the anaplastic lymphoma kinase (ALK) rearrangement are the two most common druggable targets in non-small cell lung cancer (NSCLC)." (PMID 29164298, 2018). "In arm B, EGFR-mutant non-small-cell lung cancer patients will be switched from gefitinib to osimertinib treatment as soon as the T790M resistance EGFR mutation is detected in ctDNA." (PMID 29861869, 2018). "First, we examined EGFR-inhibitor resistance in the EGFR mutant non-small cell lung carcinoma (NSCLC) cell line HCC4006." (PMID 29874589, 2018). "This miRNA is down-regulated in different cancers and transfection with a miR-218-5p mimic inhibits migration and proliferation in non-small-cell lung cancer cells by targeting the epidermal growth factor receptor (EGFR)." (PMID 29899866, 2018). "In non-small cell lung cancer, EGFR inhibitors (e.g., erlotinib) are FDA approved for tumors with activating EGFR mutations, which are present at 10 and 1% in our LUAD and lung squamous cell carcinoma (LUSC) cohorts, respectively." (PMID 30053901, 2018).